PICK1 (protein interacting with PRKCA 1)
Diseases named in the same sentence as PICK1 in open-access papers (continued):
Sharing a sentence is not in itself a finding about the gene and the disease.
schizophrenia (9 papers, 2013 to 2023). A major psychotic disorder characterized by abnormalities in the perception or expression of reality. "Based on the interaction of PICK1 with CNS dopamine transporter system, the gene of PICK1 has been implicated in schizophrenia and methamphetamine abusers, and positive results have been identified." (PMID 30687223, 2018). "In addition, some polymorphisms in the PICK1 gene (rs3952, rs713729, and rs2076369) have been linked to schizophrenia, although disputed." (PMID 35455935, 2022). "Schizophrenia and cognition: some studies proposed PICK1 as a schizophrenia susceptibility gene." (PMID 35455935, 2022). "Similarly, targeted deletion of the SR-interacting protein PICK1 in mice leads to D-serine deficiency in prefrontal cortex and schizophrenia-like behavioral abnormalities." (PMID 26941605, 2016). "In addition, the DLG4 and PICK1 genes, map to chromosome 17p13.1 and 22q13.1, respectively, regions that are known schizophrenia susceptibility loci, making them ideal positional candidates to screen for schizophrenia genetic predisposition." (PMID 23936182, 2013). "We enrolled 310 patients with chronic stable schizophrenia and genotyped two SNPs (rs2076369, rs3952) of the PICK1 gene." (PMID 28507309, 2017). "Future investigations aim to explore the influences of PICK1 between cognitive dysfunction and brain pathology of schizophrenia are necessary." (PMID 28507309, 2017). "By performing a three staged genetic analysis in independent cohorts of Japanese and Chinese schizophrenia patients, our study aimed to investigate the role of genomic variants in DLG4, DLG1, PICK1 and MDM2 in determining the predisposition to schizophrenia." (PMID 23936182, 2013). "In this study, we first performed family-based association analysis of genetic variants in the PSD genes; DLG4, DLG1, PICK1 and MDM2 using Japanese schizophrenia pedigrees." (PMID 23936182, 2013). "How might ICA69 and PICK1 regulate complex neurological disorders that involve variable behavioral phenotypes in autism spectrum disorders, intellectual disability, schizophrenia, and perhaps also Alzheimer's disease?" (PMID 37251649, 2023). "It is also important to mention that the PICK1 gene was not among the 108 schizophrenia loci identified by a genome-wide association study of up to 36,989 schizophrenic cases and 113,075 controls." (PMID 35455935, 2022). "Through its distinctive structures, PICK1 interacts with broad ranges of neurotransmitter receptors, transporters, and enzymes to influence the synaptic function, resulting in neurological damage such as Parkinson's disease, epilepsy, and schizophrenia." (PMID 30402043, 2018). "A recent study showed that combined application of D-serine related drugs and classical antipsychotic drugs could improve the cognition of patients with schizophrenia, indicating the potential role of PICK1 in cognitive function." (PMID 30687223, 2018). "Additionally, PICK1 may involve in neurological disorders such as schizophrenia, via its interaction with subunit 2 of AMPA receptor (GluA2) and its influence on the excitatory synapse activity." (PMID 28507309, 2017). "While the candidate genes used to construct this network were selected using evidence for disease implication derived from two different approaches, the network includes many additional genes of potential relevance to schizophrenia (e.g., GRIA2, GRIN1, GRIN2B, HOMER1, PICK1, and SNAP25)." (PMID 25484875, 2014).
Alzheimer disease (7 papers, 2017 to 2023). A progressive, neurodegenerative disease characterized by loss of function and death of nerve cells in several areas of the brain leading to loss of cognitive function such as memory and language. "Additionally, loss of ICA69 or PICK1 in mice is known to develop late-onset diabetes, and elderly diabetics are at a high risk for dementia including Alzheimer's disease." (PMID 37251649, 2023). "Inhibiting PICK1–GluA2 interactions may be an effective therapy for Alzheimer disease and, potentially, could address substance use disorders as well." (PMID 35954295, 2022). "Moreover, PICK1 has been evoked as a putative target in ischemia, Alzheimer's disease, and Parkinson's disease." (PMID 32352640, 2020). "That is, PICK1 may modulate spatial working memory in schizophrenic patients, as well as in mouse models of Alzheimer’s disease." (PMID 28507309, 2017). "It has been shown that the down regulation of AMPA receptors can lead to progression in neurodegenerative diseases such as Alzheimer disease, thus suggesting that inhibiting the PICK1-GluA2 interaction that is responsible for such down regulation may be an effective therapy for Alzheimer disease." (PMID 35954295, 2022). "Whether PICK1 influences on Alzheimer’s disease of human beings deserves to be deeply studied." (PMID 28507309, 2017). "The emerging role of the PICK1-GluA2 interaction in synaptic biology prompted us to search for small molecule inhibitors of this protein-protein interaction to stabilize AMPA receptors on the cell surface and promote synaptic structure and function as a potential treatment for Alzheimer’s disease." (PMID 30194389, 2018).
Sepsis (7 papers, 2018 to 2024). Sepsis is defined as life-threatening organ dysfunction caused by a dysregulated host response to infection. "The main finding of this research is that PICK1 deficiency causes a disruption of autophagy progress and amplifies the damage in sepsis-induced ALI." (PMID 30402043, 2018). "Our data demonstrated that PICK1 deficiency caused disruption of autophagic flux and aggravated lung damage induced by sepsis." (PMID 30402043, 2018). "We concluded that PICK1 deficiency inhibited the autophagic flux and amplify the damage in the sepsis-induced ALI." (PMID 30402043, 2018). "The current study developed a more comprehensive role of PICK1, and the dysfunction of autophagy caused by its deficiency is detrimental to sepsis-induced ALI." (PMID 30402043, 2018). "In this study, we explored the function of PICK1 and demonstrated the underlying molecular mechanism on autophagy progress through setting sepsis models in vivo and vitro." (PMID 30402043, 2018). "However, more serious damage was caused by PICK1 deficiency indicating that the disrupted autophagic flux was harmful to sepsis-induced ALI." (PMID 30402043, 2018). "Besides, PICK1 deficiency aggravated sepsis-induced acute lung injury through lysosomal injury." (PMID 34307672, 2021). "The impact of the PICK1 protein on the TLR4 signaling pathway was further investigated by detecting mouse macrophages, which revealed that PICK1 knockout sepsis-induced liver injury mice had the strongest NF-κB activity in sepsis-induced liver injury mice." (PMID 37488153, 2023). "PICK1 is an important regulatory protein involved in brain-related diseases and plays a protective role in sepsis." (PMID 37753078, 2023). "The present study developed a mouse model of sepsis-induced liver injury to better explore the potential mechanism of PICK1." (PMID 37488153, 2023). "By observing the livers of mice, the severity of liver injury in the sepsis-induced liver injury mouse model was found to be highest in mice with PICK1 knockout." (PMID 37488153, 2023). "We performed in vitro and in vivo experiments to explore the role of protein kinase C-binding protein 1 (PICK1), an intracellular transporter involved in oxidative stress-related neuronal diseases, in sepsis-related acute kidney injury (AKI)." (PMID 34307672, 2021). "To investigate the importance of PICK1 in autophagy regulation, we established sepsis models for observation at 4 h, 8 h, and 24 h." (PMID 30402043, 2018). "The study offers a potential mechanism of PI3K-Akt-mTOR-signaling pathway with PICK1 and autophagic activity in the setting of sepsis." (PMID 30402043, 2018). "However, the prognosis of PICK1 in sepsis mice remains to be investigated, and we hope to study it in future experiments." (PMID 37488153, 2023). "Therefore, this study posits that within sepsis-induced acute liver injury, PICK1 potentially exerts a protective role on the liver by associating with TLR4 to inhibit the release of inflammatory factors and hepatocyte apoptosis." (PMID 37488153, 2023). "Based on these findings, we hypothesize the existence of a protective mechanism involving PICK1 against sepsis-induced ALI." (PMID 37488153, 2023). "Autophagy is also protective in sepsis-induced lung injury, as a deficiency of proteins interacting with C-kinase 1 (PICK1) in mice leads to defective autophagy, and more severe acute lung injury in the cecal ligation and puncture (CLP) model of sepsis, as compared to WT animals." (PMID 32847034, 2020). "As previous research has confirmed, autophagy was activated at the early stage of sepsis; we speculate that PICK1 participates in autophagy progression related to sepsis-induced ALI." (PMID 30402043, 2018). "It is the first time to report the role of PICK1 with autophagy in sepsis-induced ALI." (PMID 30402043, 2018). "As autophagic flux was disrupted in PICK1−/− mice, we wondered whether it plays a protective or pernicious role in sepsis-induced ALI." (PMID 30402043, 2018).
Sepsis (continued). "To confirm the relationship between PICK1 and autophagy, we induced sepsis in PICK1−/− mice." (PMID 30402043, 2018). "Nevertheless, whether PICK1 can regulate the inflammatory response mediated by the TLR4/NF-κB pathway in sepsis and the underlying mechanisms involved have not yet been reported." (PMID 37488153, 2023). "In conclusion, the knockdown of PICK1 appeared to modulate inflammatory factors by activating the TLR4/NF-κB signaling pathway, thereby exacerbating hepatic damage induced by sepsis." (PMID 37488153, 2023). "In conclusion, this work explored the impact of PICK1 on the regulation of TLR4 and NF-κB expression, as well as the sepsis-induced ALI in CLP mice, providing a research direction for the prevention and treatment of the sepsis-induced ALI." (PMID 37488153, 2023). "Together, these in vivo and in vitro results indicate that mice lacking PICK1 experienced disrupted autophagy progress after sepsis." (PMID 30402043, 2018).
diabetes (5 papers, 2013 to 2023). "Here, we identify 4 coding variants in the PICK1 gene from a whole-exome screening of Danish patients with diabetes that each involve a change in positively charged residues in the PICK1 BAR domain." (PMID 35077398, 2022). "Deficiency of PICK1 or ICA69 in mice led to diabetes-like phenotypes characterized by glucose intolerance, insufficient insulin release, and elevated proinsulin secretion." (PMID 23630453, 2013). "Loss of PICK1 and ICA69 leads to impaired conversion of proinsulin to mature insulin, and PICK1 KO mice display diabetes-like symptoms such as glucose intolerance, insufficient insulin release, and elevated proinsulin secretion." (PMID 26868290, 2016). "This PICK1-activated pathway increases GLUT2 expression and functionally protects pancreatic β cells, promoting insulin secretion and slowing the progression of type 2 diabetes mellitus." (PMID 37123284, 2023). "As a result, mice lacking either ICA69 or PICK1 developed diabetes-like phenotypes, such as glucose intolerance, due to defective insulin secretion when they turned half to 1 year old." (PMID 37251649, 2023). "This suggests that PICK1 and ICA69 could be involved in the pathogenesis of diabetes, but it remains to be examined whether abnormalities of PICK1 and ICA69 are indeed present in type 2 diabetes, and what exact roles they may play in the disease." (PMID 23630453, 2013).
Parkinson disease (5 papers, 2013 to 2021). A progressive degenerative disorder of the central nervous system characterized by loss of dopamine producing neurons in the substantia nigra and the presence of Lewy bodies in the substantia nigra and locus coeruleus. "Parkin, a protein directly linked to Parkinson's disease (PD), functions as an E3 ligase to PICK1." (PMID 23431475, 2013). "Previous studies have shown that PICK1 interacts with various neurotransmitter receptors, enzymes, and transporters through its unique structure to affect synaptic function, leading to nerve damage, such as epilepsy and Parkinson's disease." (PMID 34307672, 2021).
prostate carcinoma (5 papers, 2019 to 2024). A carcinoma that arises from epithelial cells of the prostate gland. "Furthermore, an upregulation of PICK1 was associated with a decrease in the metastasis potential of prostate cancer cell lines, as well as inhibition of the invasive capabilities of bone metastasis of prostate cancer cells in a mouse intracardial model." (PMID 35774118, 2022). "Both were associated with prostate cancer, though PSCA is associated with advanced stages of prostate cancer, and upregulation of PICK1 is associated with a decrease in the metastatic potential." (PMID 35774118, 2022). "In accordance with these findings, the expression of PICK1 decreases in prostate cancer cells metastasizing to bone and negatively correlates with PSA levels, Gleason grade, and the presence of bone metastasis in patients." (PMID 31842336, 2019). "Specifically, PICK1 upregulation in prostate cancer cells inhibited nuclear translocation of pSMAD2/3 and suppressed the expression of TGF-β target genes both in the presence and absence of TGF-β." (PMID 31842336, 2019). "Similarly, in prostate carcinoma cells, PICK1 suppresses both cell invasion and migration and bone metastasis." (PMID 38664379, 2024). "The stimulatory TGF-β effects on prostate cancer progression are counteracted by PICK1." (PMID 31842336, 2019). "Moreover, overexpression of PICK1 reduced the motility and invasiveness of prostate cancer cells." (PMID 31842336, 2019). "Moreover, protein interacting with PRKCA 1 (PICK1), a negative regulator of the TGF-β pathway, can repress prostate cancer metastasis to bone." (PMID 34829922, 2021).
epilepsy (4 papers, 2018 to 2023). A brain disorder characterized by episodes of abnormally increased neuronal discharge resulting in transient episodes of sensory or motor neurological dysfunction, or psychic dysfunction. "Some of them were already known to play a role in AD: PICK1 is involved in synaptic scaling; AP2A2 is involved in receptor-mediated endocytosis; SYT7 is regulated by amyloid precursor protein; and KIF5B is critical for GABAAR transport, and its deletion causes epilepsy." (PMID 36538112, 2023).
glioma (4 papers, 2021 to 2025). A benign or malignant brain and spinal cord tumor that arises from glial cells (astrocytes, oligodendrocytes, ependymal cells). "Each glioma patient was assigned a risk score according to the following formula: risk score = (0.2433)*RAB13 + (0.4201)*LYPLA1 + (0.0013)*GAS1 + (−0.0463)*VAMP2 + (0.5165)*CNIH4 + (0.3109)*PICK1 + (−0.0864)*RAB6B + (0.0978)*GOLT1." (PMID 37062068, 2023). "Finally, our tissue-specific analyses highlight five candidate tissues (cerebellum, cortex, and the putamen, caudate and nucleus accumbens basal ganglia) and four genes (JAK1, STMN3, PICK1 and EGFR) which had causal evidence for affecting glioma risk in further research." (PMID 33504897, 2021).
type 2 diabetes (4 papers, 2013 to 2023). "Finally, both in a Drosophila model of type 2 diabetes and in high-fat-diet-induced obese mice, we observed up-regulation of PICK1 mRNA expression." (PMID 23630454, 2013). "Finally, we found that PICK1 expression levels were raised in a fly model of type 2 diabetes and in high-fat-diet-induced obese mice." (PMID 23630454, 2013). "Furthermore, PICK1 mRNA expression is up-regulated in both a Drosophila model of type 2 diabetes (T2D) and in high-fat-diet-induced obese mice." (PMID 23630454, 2013).
Pain (3 papers, 2020 to 2022). An unpleasant sensory and emotional experience associated with actual or potential tissue damage, or described in terms of such damage. "We conclude that PICK1 constitutes a valid drug target for the treatment of inflammatory and neuropathic pain conditions without the side effects and abuse liability associated with current pain medication." (PMID 35455935, 2022).
astrocytic tumor (2 papers, 2020 to 2024). A glial tumor of the brain or spinal cord showing astrocytic differentiation. "As documented previously, the expression of PICK1 is downregulated in grade IV astrocytic tumor cell lines and is associated with tumor progression." (PMID 38664379, 2024). "For example, PICK1 expression is down-regulated in grade IV astrocytic tumor cell lines and also in clinical cases of the disease in which grade IV tumors have progressed from lower-grade tumors." (PMID 32336285, 2020).
breast tumors (2 papers, 2014 to 2020). "It was reported that PICK1 negatively or positively regulated the neoplastic infiltration of astrocytic or breast tumors." (PMID 32336285, 2020). "Moreover, a negative correlation between PICK1 expression and TβRI or p-Smad2 levels is observed in human breast tumors." (PMID 32336285, 2020).
dementia (2 papers, 2017 to 2023). Loss of intellectual abilities interfering with an individual's social and occupational functions. "Besides, whether genetic variation of PICK1 also affects the category fluency of patients with dementia of the Alzheimer type deserves studies too." (PMID 28507309, 2017).
Glucose intolerance (2 papers, 2013 to 2016). Glucose intolerance (GI) can be defined as dysglycemia that comprises both prediabetes and diabetes. "The roles of PICK1 and ICA69 in insulin trafficking provide the basis to understand the glucose intolerance and insulin maturation defects found in PICK1 and ICA69 KO mice." (PMID 23630453, 2013).
Impaired glucose tolerance (2 papers, 2013). An abnormal resistance to glucose, i.e., a reduction in the ability to maintain glucose levels in the blood stream within normal limits following oral or intravenous administration of glucose. "These ICA69 KO mice displayed similar glucose metabolic defects as the PICK1 KO mice, with decreased body weight, increased food/water intake, and impaired glucose tolerance due to insulin deficiency." (PMID 23630453, 2013). "They began by showing that loss of PICK1 led to impaired glucose tolerance and lowered serum levels of insulin." (PMID 23630455, 2013). "Islet cells contained an excess of immature secretory vesicles, and a deficiency of mature ones, indicating that loss of PICK1 was interfering with the maturation of insulin-containing vesicles, accounting for reduction in serum insulin and impaired glucose tolerance." (PMID 23630455, 2013).